PLK4 (polo like kinase 4)
Diseases named in the same sentence as PLK4 in open-access papers (continued):
Sharing a sentence is not in itself a finding about the gene and the disease.
liver cancer (7 papers, 2012 to 2025). An epithelial or non-epithelial malignant neoplasm that arises from the liver. "On the contrary, overexpression of PLK4 was also shown to be associated with poor prognosis in hepatic cancer patients." (PMID 41488365, 2025). "Herein, we found a significant association between rs3811741, located in the PLK4 intron, and liver cancer risk (OR = 1.26, P = 9.81 × 10−5)." (PMID 31489978, 2019). "Although PLK4 expressed at lower levels in somatic tissues compared to the testis, the risk allele A of rs3811741 was associated with increased PLK4 expression in liver cancer tissues." (PMID 31489978, 2019). "The risk allele A of rs3811741 was associated with increased PLK4 expression in liver cancer tissues, implying that it may be an oncogenic event." (PMID 41488365, 2025). "TEC kinase phosphorylation regulates PLK4, which influences liver cancer metastasis and centriole duplication." (PMID 40565600, 2025). "In TCGA database, we discovered that PLK4 was aberrantly activated and overexpressed in liver cancer tissues, in contrast with adjacent tissues." (PMID 31489978, 2019). "Less chances of bearing spontaneous lung and liver cancer were recorded in PLK4+/+ mice, compared with PLK4+/− littermates." (PMID 22829937, 2012). "Interestingly, there are reports of both the upregulation and downregulation of PLK4 in hepatic cancer." (PMID 41488365, 2025). "We then first demonstrated that poly‐ADP‐ribose polymerase 1/2 (PARP1/2) inhibitor, talazoparib, could increase the expression of lncRNA PLK4 in liver cancer cells." (PMID 32243714, 2020). "Interestingly, compared to normal samples, one of the most significantly down‐regulated lncRNAs in liver cancer samples was lncRNA PLK4 (antisense transcripts)." (PMID 32243714, 2020). "Importantly, we showed that talazoparib‐induced lncRNA PLK4 could function as a tumour suppressor gene by Yes‐associated protein (YAP) inactivation and induction of cellular senescence to inhibit liver cancer cell viability and growth." (PMID 32243714, 2020).
lung adenocarcinoma (7 papers, 2019 to 2025). A carcinoma that arises from the lung and is characterized by the presence of malignant glandular epithelial cells. "Overexpression of POLQ increased somatic mutation load and Polo-like kinase 4 (PLK4) overexpression, which induces centrosome amplification and is associated with an advanced pathologic stage in lung adenocarcinoma." (PMID 39520627, 2024). "Prognostic analysis of PLK4 expression and data analysis of its association with the somatic mutation and drug resistance through clustering were performed using the Cancer Genome Atlas-lung adenocarcinoma (TCGA-LUAD) dataset." (PMID 37760631, 2023). "It was reported that a higher methylation level of PLK4 was significantly related to the favorable survival probability of patients with lung adenocarcinoma." (PMID 41488365, 2025). "Co-expression of PLK4 and POLQ caused polyploidy where POLQ may have contributed to resistance to DSBs and promoted cancer progression in lung adenocarcinoma." (PMID 41488365, 2025).
prostate carcinoma (7 papers, 2019 to 2025). A carcinoma that arises from epithelial cells of the prostate gland. "Recently, our laboratory reported that PLK4 overexpression induced centrosome amplification in prostate cancer tissues as compared to prostatic hyperplasia or benign prostate tissues." (PMID 41488365, 2025). "Another study on prostate cancer cells showed that PLK4 expression was reduced upon treatment with a natural product called Fraxetin, which suppressed the proliferation, migration, and invasion of cells." (PMID 41488365, 2025). "Collectively, Fraxetin acted as a cancer suppressor in prostate cancer through inhibiting PLK4 expression thereby inactivating PI3K/Akt signaling." (PMID 35387563, 2022). "The specific-binding mechanism between fraxetin and PLK4 as well as the verification of the current findings on other prostate cancer cell lines are the aim our following investigations." (PMID 35387563, 2022). "Notably, a previous study reported that CAND1 promoted PLK4-regulated centriole over-duplication in prostate cancer, indicating the potential role of PLK4 in prostate cancer." (PMID 35387563, 2022). "In addition, CAND1 overexpression has been shown to promote the proliferation of prostate cancer by stabilizing PLK4." (PMID 36292029, 2022). "Importantly, we found that the anti-cancer effect of Fraxetin on prostate cancer may depend on inhibiting PLK4 expression thereby inactivating PI3K/Akt signaling." (PMID 35387563, 2022). "Therefore, we hypothesized that Fraxetin might exerted anti-cancer effect on prostate cancer through regulating PLK4 expression, subsequently affecting PI3K/Akt signaling." (PMID 35387563, 2022). "This was observed in prostate cancer cells, where CAND1 upregulation reduced ubiquitination and enhanced PLK4-mediated centriole amplification." (PMID 41488365, 2025). "The latent regulatory mechanism of Fraxetin related to PLK4 and PI3K/Akt signaling in prostate cancer progression was explored." (PMID 35387563, 2022). "In addition, treatment with PLK4 inhibitors CFI-400945 and centrinone B reduced migration, invasion, and proliferation of both androgen-responsive and androgen-independent prostate cancer cells." (PMID 41488365, 2025).
acute myeloid leukemia (6 papers, 2022 to 2025). Acute myeloid leukemia (AML) is a group of neoplasms arising from precursor cells committed to the myeloid cell-line differentiation. "TCGA database analyses of tumor tissues from 33 cancer types showed that PLK4 mRNA expression levels were different across tumor types and exhibit the highest level in acute myeloid leukemia (LAML)." (PMID 36620611, 2022). "However, roles and the mechanism of PLK4 in the leukemiagenesis of acute myeloid leukemia (AML) remain unclear." (PMID 36051696, 2022).
pancreatic cancer (6 papers, 2015 to 2025). "These limited number of studies provide evidence of PLK4’s association with pancreatic cancer." (PMID 41488365, 2025). "Overexpression of PLK4 and centriole overduplication are recognized as markers of poor prognosis in aggressive pancreatic cancer." (PMID 41488365, 2025). "Additional detailed studies are needed to define the role and functional significance of PLK4 in pancreatic cancer." (PMID 41488365, 2025). "The present study evaluates the efficacy of CFI-400945 in a panel of patient-derived pancreatic cancer xenografts displaying a range of growth rates, magnitudes of tumor hypoxia and PLK4 mRNA expression." (PMID 27902970, 2017). "Plk4 transcription upregulation was also observed in the oral cavity, cervical and pancreatic cancers (at least one probe set shows a pattern of upregulation in each data set)." (PMID 26439168, 2015). "Hence PLK4 inhibition disrupts mitosis, and offers a novel approach to treating chromosomally unstable cancers, including pancreatic cancer." (PMID 27902970, 2017). "Here, we reveal a requirement for NUAK1 to sustain proliferation of pancreatic cancer cells in vitro and identify a conserved role for NUAK1 in governing centrosome replication through GSK3β‐dependent control of PLK4 protein levels." (PMID 36975767, 2023).
Azoospermia (5 papers, 2021 to 2025). Absence of any measurable level of sperm,whereby spermatozoa cannot be observed even after centrifugation of the semen pellet. "It has been reported that individuals with a 13 base pair deletion or a missense mutation in PLK4 exhibit a combination of non-obstructive azoospermia and Sertoli cell only (SCO) syndrome." (PMID 38943004, 2024). "Thus, the present study, in relation to the individual previous studies, aims to identify SPA17, PPP1R36, AURKA, TRIP13, PLK4, CCDC90B, and CCDC91 genes as important biomarkers of both teratozoospermia- and azoospermia-associated infertility in men." (PMID 36292606, 2022). "Next-generation sequencing has contributed to the identification of several unknown genetic alterations in the context of male infertility and azoospermia including FANCA, PLK4, WKN3, MEI1, ADAD2, and TEX11." (PMID 40747475, 2025).
endometrial cancer (5 papers, 2022 to 2025). Primary or metastatic malignant neoplasm involving the endometrium (mucous membrane that lines the endometrial cavity). "This study aimed to explore the associations of tumor PLK4 protein expression with tumor characteristics and survival in endometrial cancer (EC) patients who underwent surgical resection." (PMID 38326803, 2024). "Interestingly, PLK4 activity was correlated to KIFC1, where KIFC1 overexpression promoted the expression of PLK4 and centrosome amplification in endometrial cancer HEC-1A cells, suggesting the importance of PLK4 in the progression of endometrial cancer." (PMID 41488365, 2025).
multiple myeloma (5 papers, 2013 to 2025). "Inhibition of PLK4 by centrinone B also helps to overcome resistance to lenalidomide in multiple myeloma cells." (PMID 41092110, 2025). "Expression of some genes connected with centrosome formation and function (AURKA, AURKB, CETN2, and PLK4) was significantly different between hyperdiploid and non-hyperdiploid myeloma patients." (PMID 23522059, 2013).
ovarian carcinoma (5 papers, 2017 to 2025). A malignant neoplasm originating from the surface ovarian epithelium. "Along this line, a recent preprint documents heightened cell death susceptibility of PLK4-overexpressing ovarian cancer cells toward carboplatin treatment and improved overall survival and therapy responsiveness of patients showing centrosome amplification." (PMID 38552015, 2024). "We use an inducible PLK4 overexpression system in ovarian cancer cell lines to induce centrosome amplification in isogenic backgrounds." (PMID 39236086, 2024). "To study the influence of centrosome amplification on the response to Carboplatin and Paclitaxel, we used an inducible PLK4 overexpression system (PLK4OE) in the epithelial ovarian cancer cell line OVCAR8." (PMID 39236086, 2024). "Targeting PLK4 with the small molecule inhibitor YLZ-F5 prevents human ovarian cancer growth by inducing aneuploidy and promotes apoptosis via activation of caspases-3/9 and impairs cell migration." (PMID 34065956, 2021). "The role of PLK4 in ovarian cancer is of special interest for this review and will be discussed further below." (PMID 34065956, 2021). "High expression of PLK4/PLK1 on mRNA and protein level is linked to an advanced pathological stage in epithelial ovarian cancer and PLK4-transfected ovarian cell lines show accelerated proliferation." (PMID 34065956, 2021). "Ovarian cancer cells were more sensitive to the depletion of STIL than to other centriolar replication factors including PLK4, SASS6 and CENPJ." (PMID 28423708, 2017). "Interestingly, in our shRNA screens, PLK4 was essential for survival of a subset of ovarian cancer cell lines, suggesting a possible difference between enzymatic and non-enzymatic functions of PLK4." (PMID 28423708, 2017). "Successful treatment of ovarian cancer remains to be a challenge and especially PLK1 and PLK4 proof to be a very promising target for diagnosis and treatment." (PMID 34065956, 2021).
bladder cancer (4 papers, 2019 to 2025). "PLK4 mRNA and protein are overexpressed in bladder cancer cell lines and tissues; downregulation of PLK4 inhibits cell proliferation and growth; high levels of PLK4 expression correlate with shorter overall survival (OS)." (PMID 41092110, 2025). "who successfully established PLK4 knockdown cell lines of bladder cancer cell, followed by RNA-seq analysis." (PMID 36620611, 2022). "We demonstrate that Polo‐like kinase 4 (PLK4) is overexpressed in human bladder cancer (BC) cell lines and tissues, and its overexpression correlates with poor prognosis." (PMID 34342940, 2021). "Together, these observations indicate that PLK4 and AURKB/C act redundantly to promote ACM-stimulated cell motility in various cancers and are associated with more aggressive breast and bladder cancers." (PMID 31142743, 2019). "Furthermore, abnormal expression of PLK4, AURKB and DAAM1 is associated with poor outcomes in breast and bladder cancers." (PMID 31142743, 2019). "Similarly, analysis of expression by RNA-seq in a cohort of 158 bladder cancer patients revealed that elevated expression of AURKB and PLK4 was associated with high-grade disease, in contrast to GAPDH, which was expressed similarly in both grades." (PMID 31142743, 2019). "However, the role of PLK4 in human bladder cancer (BC) remains unclear." (PMID 34342940, 2021).
breast tumor (4 papers, 2011 to 2025). "In another study, PLK4 overexpression was found in 26% of all breast tumors and 48% of TNBC." (PMID 41092110, 2025). "Furthermore, PLK4-driven centrosome amplified breast tumour cells are highly sensitive to Stat3 inhibitors." (PMID 28474672, 2017). "PLK4 inhibition might be a useful therapeutic strategy, especially for TRIM37 amplified breast tumors, as a stand-alone modality or in combination with other treatment modalities to synergize their anticancer effects and/or overcome resistance." (PMID 41092110, 2025).
lymph node metastasis (4 papers, 2022 to 2025). "In addition, the expression of PLK4 was associated with pathological grading and lymph node metastasis in human CRCs." (PMID 35912011, 2022).
lymphoma (4 papers, 2021 to 2025). A malignant (clonal) proliferation of B- lymphocytes or T- lymphocytes which involves the lymph nodes, bone marrow and/or extranodal sites. "To better understand the role of BAX in CFI sensitivity we generated isogenic BAX wild-type and BAX-deficient clones from two PLK4 sensitive lymphoma lines (OCI-LY19 and Z-138)." (PMID 36934096, 2023). "Together, we report a synergistic drug combination based on the biological properties of lymphoma, which are ill-prepared for polyploidy and susceptible to combined PLK4 and BCL-2 inhibition to induce and eliminate polyploid cells with negligible toxicity in healthy animals." (PMID 36934096, 2023). "Accordingly, BAX-deficient lymphomas are highly resistant to the PLK4 inhibitor CFI-400945." (PMID 36934096, 2023). "Together, these results indicate that while CFI and S63845 depend solely on BAX, venetoclax can trigger BAX-independent cell death, most likely through BAK, and enable the elimination of PLK4-inhibited lymphoma cells." (PMID 36934096, 2023). "Next, we explored the ability of BCL-2 and MCL-1 inhibitors to enhance PLK4 action in lymphoma." (PMID 36934096, 2023). "Here, we report a therapeutic combination of inhibitors of the Polo-like kinase 4 and BCL-2 that trigger genomic instability and cell death in aggressive lymphomas." (PMID 36934096, 2023). "We then tested the combination of PLK4 and BCL-2 inhibitors in a primary transplanted patient-derived GCB-DLBCL lymphoma model (PDX)." (PMID 36934096, 2023). "Since PLK4 is involved in mitotic entry and exit, we next examined the effects of CFI-400945 on lymphoma cell cycle progression." (PMID 34162828, 2021). "Venetoclax and the PLK4 inhibitor CFI-400945 are already in clinical use, and our data provide a mechanistic rationale for testing their combination in the treatment of aggressive lymphomas." (PMID 36934096, 2023).
male infertility (4 papers, 2017 to 2025). The inability of the male to effect fertilization of an ovum after a specified period of unprotected intercourse. "We mainly describe the SYCP3 and PLK4 genes that we have studied in our laboratory, and add comments on other genes associated with human male infertility." (PMID 29259455, 2017). "In this review, the SYCP3 and PLK4 genes that have been studied in the authors’ laboratory are mainly described and comments on other genes that are associated with human male infertility have been added." (PMID 29259455, 2017). "Five of these genes were characterized as male infertility‐related genes, including Polo‐like kinase 4 (PLK4), AGTPBP1, KISS1 receptor, Meiosis Expressed Gene 1 (MEIG1), and Piwi Like RNA‐Mediated Gene Silencing 2 (PIWIL2)." (PMID 37937809, 2024).
non-small cell lung carcinoma (4 papers, 2023 to 2026). A group of at least three distinct histological types of lung cancer, including non-small cell squamous cell carcinoma, adenocarcinoma, and large cell carcinoma. "For example, one study showed that increased PLK4 mRNA expression is linked with tumor stage in non-small cell lung cancer patients." (PMID 38326803, 2024).